BAP1 (BRCA1 associated deubiquitinase 1)
Diseases named in the same sentence as BAP1 in open-access papers (continued):
Sharing a sentence is not in itself a finding about the gene and the disease.
uveal melanoma (continued). "Depletion of BAP1 in uveal melanoma cells resulted in a loss of differentiation and gain of stem-like properties, including expression of stem cell markers, increased capacity for self-replication, and enhanced ability to grow in stem cell conditions." (PMID 23915344, 2013). "In this study, we wished to determine the function of BAP1 in uveal melanoma, where BAP1 loss appears to play a specific role in tumor progression and acquisition of metastatic capacity." (PMID 23915344, 2013). "Given these unexpected findings, we wished to gain insights into the role of BAP1 loss in uveal melanoma progression by analyzing the changes in global gene expression associated with BAP1 depletion." (PMID 23915344, 2013). "Germline BAP1 mutations are associated with a novel cancer syndrome characterized by malignant mesothelioma, uveal melanoma, cutaneous melanoma and MBAITs, and possibly by other cancers." (PMID 22935333, 2012). "Malignant mesothelioma, uveal melanoma, cutaneous melanoma, and MBAITs prevalence was significantly higher in the BAP1-mutated cohort (p ≤ 0.001)." (PMID 22935333, 2012). "We demonstrate that germline BAP1 mutations are associated with a novel cancer syndrome characterized by MM, uveal melanoma (UVM), CM, MBAITs and possibly by other tumors." (PMID 22935333, 2012). "In uveal melanoma, exome sequencing has recently identified inactivating mutations to BAP1 in 84% of metastasizing tumors." (PMID 24212610, 2010). "This highlights the prognostic implication of BAP1 mutations in uveal melanoma." (PMID 41262171, 2025). "A comprehensive meta-analysis of all published BAP1-mutated families demonstrated strong associations between BAP1 mutations and malignant mesothelioma, uveal melanoma, and cutaneous melanoma, thereby defining a distinct hereditary cancer syndrome now referred to as the BAP1 cancer syndrome." (PMID 41561288, 2025). "In addition, the presence of uveal melanoma-related hotspot mutations (including BAP1, SF3B1, and GNAQ/11) in CM has been linked to advanced disease and increased risk for metastasis and death." (PMID 40521590, 2025). "Furthermore, it is critical to note that BAP1 mutations are more frequent in uveal melanoma than cutaneous melanoma, though they can be found in a subset of cutaneous melanoma." (PMID 40842586, 2025). "BIMs were originally described in patients with germline inactivating BAP1 mutations, which cause an autosomal dominant tumour predisposition syndrome with increased risk of uveal melanoma, mesothelioma, meningioma, renal cell carcinoma, and cutaneous melanoma." (PMID 39976080, 2025). "Although uveal melanoma prognosis is very strongly correlated with monosomy 3 and the loss of BAP1, we wondered whether any of the DE genes identified above were correlated with survival in the TCGA-UVM database." (PMID 39804140, 2025). "Germline mutations in BAP1 inherited in an autosomal dominant manner, or somatic mutations were confirmed to cause BAP1-Tumor Predisposition Syndrome, which increases the risk of developing uveal melanoma and several other cancers." (PMID 38540335, 2024). "Does the presence of mutations in the GNAQ or GNA11 gene, absence of mutations in the BRAF V600 gene, or association of mutation in the BAP1 gene with metastasis that belies its unique stemness origins in uveal melanoma bestow its distinct prognostic and/or predictive dispositions?" (PMID 38539487, 2024). "In addition, we found elevated IGF1 mRNA expression in BAP1-mutant uveal melanomas, where higher expression levels are associated with a poorer prognosis." (PMID 38969833, 2024). "However, we did not observe a significant difference in overall survival of stage lV non-uveal melanoma patients harboring BAP1 mutations compared to published BAP1 wildtype cohorts." (PMID 38903495, 2024).
uveal melanoma (continued). "The progression of uveal melanoma relies on a second genetic driver event, such as the inactivation of BAP1 (about 60% of cases) on chromosome 3p21, mutation in the Splicing Factor 3b Subunit 1 (Spliceosome Factor SF3B1) (about 25% of cases), or EIF1AX mutation (about 15–17% of cases)." (PMID 38732371, 2024). "As BAP1 is frequently mutated in patients with uveal melanoma and seems to be highly prevalent in liver metastasis, with a prevalence of approximately 95%, we tested whether this combination is effective against uveal melanoma as well." (PMID 38054839, 2024). "BAP1 is an important tumor suppressor, mutated in sporadic uveal melanomas, mesotheliomas, renal cell carcinomas, hepatocellular carcinomas, and to a lesser extent other cancers, while BAP1-interacting ASXL proteins are commonly mutated in myeloproliferative disorders." (PMID 38529289, 2024). "Furthermore, it is well-documented that BAP1 mutations in uveal melanoma strongly correlate with BAP1 expression in immunohistochemical staining." (PMID 38903495, 2024). "Hence, our discovery that GZ17-6.02 is enhancing BAP1 expression favors increased expression from the wild type unmutated BAP1 allele in uveal melanoma cells." (PMID 38758815, 2024). "Furthermore, uveal melanoma expressed high levels of the tumor necrosis factor superfamily member 4-1BB ligand, particularly in tumors with monosomy 3 and BAP1 mutations." (PMID 38191418, 2024). "Patients who declined treatment may have differed from those who enrolled, particularly in unmeasured factors such as chromosome 3 or 8q aberrations, BAP1 mutations, and gene expression profiles—key prognostic markers in uveal melanoma." (PMID 39594794, 2024). "Primary uveal melanomas consist of four cell types; normal, spindle A, spindle B, and epithelioid cells where the last-mentioned has lower expression levels of the BReast CAncer gene associated protein (BAP-1)." (PMID 39201396, 2024). "Uveal melanoma, a malignancy of the eye, is affected by several risk factors, including fair skin, blonde hair, light eye color, the presence of choroidal nevus, and the germline mutation in the breast cancer 1-associated protein 1 (BAP1)." (PMID 38724687, 2024). "Additionally, the BAP1 gene is associated with uveal melanoma more than cutaneous melanoma and uveal melanoma has a higher risk of metastasis compared to cutaneous melanoma." (PMID 38090659, 2023). "BAP1 mutation is prevalent in other cancer types such as uveal melanoma and malignant mesothelioma." (PMID 37260182, 2023). "However, another study reported that loss of BAP1 expression correlates with an immunosuppressive microenvironment in uveal melanoma, suggesting the immunotherapy resistance." (PMID 37813891, 2023). "Recent research has shown that BAP1 methylation at a single genomic region is highly correlated with BAP1 mutations, BAP1 genomic copy loss, and protein levels that are related to uveal melanoma metastasis, while BAP1 deletion in the initial cancer is related to the disease." (PMID 37124608, 2023). "Interestingly, several studies reported patients harboring a BAP1 mutation in uveal melanoma are at risk for metastasis, suggesting a similar risk within meningioma patients." (PMID 36641486, 2023). "In uveal melanoma, the activity of verteporfin appears, however, to be more pronounced in cells carrying the wild-type form of BAP1 than in cells in which BAP1 function is abolished by mutations and monosomy of chromosome 3, as is typical for UM with high metastatic risk." (PMID 36765842, 2023). "BAP1-tumor predisposition syndrome is an autosomal dominant disease that increases a patient’s risk of malignancies including uveal melanoma followed by the following neoplasms in decreasing order: mesothelioma, cutaneous melanoma, renal cell carcinoma, and basal cell carcinoma." (PMID 38090659, 2023).
uveal melanoma (continued). "Therefore, loss of BAP1 expression is associated with an immunosuppressive microenvironment in uveal melanoma, with implications for immunotherapy development 33-35." (PMID 34976173, 2022). "The BAP1 gene has emerged as a major tumor suppressor mutated with various frequencies in numerous human malignancies, including uveal melanoma, malignant pleural mesothelioma, ccRCC, intrahepatic cholangiocarcinoma, hepatocellular carcinoma, and thymic epithelial tumor." (PMID 35028006, 2022). "Somatic BAP-1 loss is found in 84% of patients with metastatic uveal melanomas." (PMID 36553016, 2022). "Mutations in BAP1 were first identified in studies of familial malignancies, which manifested as increased prevalence of rare malignancies in some families, such as malignant mesothelioma, cutaneous melanoma, and uveal melanoma." (PMID 36003792, 2022). "The observation that germline mutations of BAP1 gene are inherited in an autosomal dominant pattern, and associated with increased risk of other malignancies including cutaneous or uveal melanomas, renal cell carcinomas, linked BAP1 to a tumor predisposition syndrome." (PMID 36362209, 2022). "In addition, mutations within BAP1’s catalytic domain have been detected in different types of human cancers such as uveal melanoma and have been demonstrated as loss-of-function mutations." (PMID 35194152, 2022). "Additionally, we reported on widespread deficiency of ASS1 in a majority (74%) of 102 primary choroidal and ciliary body melanomas, despite the known 60–80% loss of BAP1 in uveal melanoma." (PMID 35466524, 2022). "BAP1 is located on chromosome 3p21.1, which is frequently lost or mutated in uveal melanoma." (PMID 36292588, 2022). "Our study demonstrates that intrinsic disorder in BAP1 may be associated with the development of uveal melanoma." (PMID 36292588, 2022). "Many studies found loss of BAP1 in uveal melanoma metastasis may be mainly involved in the progression of uveal melanoma to an aggressive, metastatic phenotype." (PMID 34739630, 2022). "BRCA1-associated protein 1 (BAP1) expression is predictive of metastasis in uveal melanoma." (PMID 34441338, 2021). "Up to 40% of uveal melanomas and 17% of malignant blue nevi contain mutations in BAP1." (PMID 35008286, 2021). "Germline heterozygous BAP1 mutations are responsible for the BAP1-cancer syndrome, an autosomal dominant condition characterized by high susceptibility to developing cancers, particularly uveal melanoma, malignant mesothelioma, cutaneous melanomas, renal cell carcinoma, and cholangiocarcinoma." (PMID 33915954, 2021). "In addition, reduced BAP1 RNA expression and protein nuclear loss have been correlated with immune modulation and poor outcomes in primary and metastatic uveal melanoma." (PMID 32944962, 2021). "Uveal melanoma is associated with BAP1 mutations in almost 3% of the cases." (PMID 34442055, 2021). "Indeed, there is an ongoing clinical trial of the PARP inhibitor niraparib in BAP1-deficient neoplasms including uveal melanoma (NCT03207347)." (PMID 34441278, 2021). "Finally, approximately 40% of uveal melanomas carry loss-of-function pathogenic variants of the BAP1 tumor suppressor gene and these variants are associated with increased metastatic risk." (PMID 34533562, 2021). "BAP1 mutations are associated with monosomy 3, which is associated with metastatic uveal melanoma." (PMID 32429485, 2020). "Furthermore, the somatic mutation of BAP1 is more abundant in highly metastatic tumors, such as uveal melanoma." (PMID 33117084, 2020). "Furthermore, BAP1 mutation in cancer cells predicts mortality and recurrence across various cancer types, including colorectal, renal, uveal melanoma, and lung adenocarcinoma, but is less predictive in others." (PMID 33105797, 2020). "Furthermore, we found mutual exclusivity of SF3B1 or BAP1 driver mutations in all patients with uveal melanoma." (PMID 32825510, 2020).
uveal melanoma (continued). "Germline mutations in BAP1, a bona fide tumor suppressor, are associated with BAP1 tumor predisposition syndrome that puts carriers at a higher risk for several cancer types including uveal melanoma, malignant mesothelioma, clear cell renal cell carcinoma, and basal cell carcinoma." (PMID 32708614, 2020). "In addition, 40% uveal melanoma present genetic alterations in BAP1, which are associated with metastasis." (PMID 32532044, 2020). "Metastatic uveal melanoma samples frequently exhibit monosomy 3 or BAP1 deficiency." (PMID 31954372, 2020). "Reduced BAP1 expression has been linked to poor prognosis and adverse tumor features in renal carcinoma, colorectal cancer, gastric adenocarcinoma, non-small cell lung cancer, gall bladder cancer and uveal melanoma." (PMID 31903168, 2019). "The Cancer Genome Atlas (TCGA) data mining indicates that high levels of FGF and/or FGF receptor (FGFR) expression are associated with reduced overall survival, chromosome 3 monosomy and BAP1 mutation in human uveal melanoma (UM), pointing to the FGF/FGFR system as a target for UM treatment." (PMID 31487962, 2019). "Focusing on the germline variants identified within genes involved in HR, most variants showing LOH were in agreement with known genotype–phenotype correlation as indicted by the observation of BRCA1/2 variants in breast, ovarian and prostate tumor samples and BAP1 variants in uveal melanoma." (PMID 31263571, 2019). "Germline mutations in BAP1 have been observed in 22% of familial uveal melanoma and could be associated with early onset." (PMID 31109147, 2019). "Interestingly, in uveal melanoma, another disease with frequent BAP1 loss, the loss of BAP1 expression is associated with an increased infiltration of CD3+ and CD8+ T cells, a finding paralleled in PeM tissues by the investigations of Shrestha and colleagues." (PMID 30914057, 2019). "In all three of our cases, ATM mutations cooccurred with pathogenic somatic variants in the BAP1 gene and two tumors have partial loss of chromosome 3, which are also relatively common event in metastasizing uveal melanoma, both associated with worse prognosis." (PMID 29769598, 2018). "Uveal melanoma (UM) is a rare malignant tumor of the eye with a frequency of 5.1 per million in the United States, and is the cancer most commonly associated with the BAP1-TPDS." (PMID 30477459, 2018). "Similarly, depletion of BAP1 results in loss of differentiation and gain of stem-like properties in uveal melanoma cells." (PMID 29018224, 2017). "According to these findings, it was proposed that SF3B1 mutations help to define a subgroup of uveal melanomas associated with metastatic risk that is intermediate between uveal melanomas with BAP1 mutations (high risk) and uveal melanomas with EIF1AX mutations (low risk)." (PMID 29156643, 2017). "In addition, germline and/or somatic mutations in BAP1 are reported in uveal melanoma, atypical epithelioid Spitz tumors, cutaneous melanoma, mesothelioma, renal cell carcinoma, lung adenocarcinoma, meningioma and many other cancers." (PMID 28404968, 2017). "In uveal melanoma, BAP1 inactivation is associated with metastasis development and worse prognosis." (PMID 29069806, 2017). "Therefore, results of our study concur with previous findings in uveal melanoma and cutaneous melanoma that, suggested that loss of nuclear BAP1 protein expression correlated with an aggressive subtype with poor survival in OMM patients." (PMID 28404968, 2017). "Although, BAP1 is associated with metastasis in uveal melanoma, its functional mechanism was unknown." (PMID 28404968, 2017). "In addition, somatic loss of the wild-type allele of BAP1 has been detected in a patient with malignant uveal melanoma and paraganglioma." (PMID 28187001, 2017).
uveal melanoma (continued). "Although less than 1% of all uveal melanoma cases are familial, studies have demonstrated that these patients carry many mutations, primarily germline mutation of BAP1, and have suggested that these mutations may be responsible for transmission in familes." (PMID 27800275, 2016). "Loss of BAP1, as is the case in monosomy 3, may predispose a patient to uveal melanoma for tumor recurrence." (PMID 25874144, 2015). "To study longer-term effects of BAP1 loss, we used short-hairpin RNA (shRNA) expressed from lentiviral vectors, which consistently achieved 70-90% depletion of BAP1 protein levels in three different uveal melanoma cell lines (OCM1A and 92.1, and Mel290)." (PMID 23915344, 2013). "We recently showed that inactivating mutations in the tumor suppressor BAP1 occur almost exclusively in class 2 tumors and are strongly associated with metastasis, suggesting that BAP1 may function as a metastasis suppressor in uveal melanoma." (PMID 23915344, 2013). "Similarly, BAP1-deficient uveal melanoma cells were less capable than control cells of anchorage independent growth in soft agar assays." (PMID 23915344, 2013). "Furthermore, ex vivo studies employing patient-derived tumor organoids (PDTOs) of uveal melanoma (UM) and clear-cell renal cell carcinoma (ccRCC) as preclinical models have substantiated the synergism of these drugs, preferentially in the context of BAP1 loss." (PMID 40754831, 2025). "As previous mentioned, mutation or deletion of BAP1 may exhibit a correlation with the expression levels of PD-L1 in certain tumor types, such as malignant peritoneal/ pleural mesothelioma, thymic carcinoma and uveal melanoma." (PMID 39350280, 2024). "When we focused on tumors potentially associated with BAP1 syndrome, we found 84 (7.4%) cases of cutaneous basal cell carcinoma, 49 (4.3%) of renal cell cancer, 46 (4.0%) of melanoma (42 cutaneous melanoma, 4 uveal melanoma), and 11 (1.0%) of hepatocellular carcinoma." (PMID 36980631, 2023). "Uveal melanoma metastatic disease has a complex development: the loss of both BAP1 alleles with mutations and chromosome 3 deletion and/or chr8q gain could drive the formation of different metastases that, after colonization of the liver, can spread to different organs." (PMID 37958591, 2023). "Interestingly, loss of BAP1 expression was found to promote T cell infiltration in uveal melanoma." (PMID 37813891, 2023). "Additionally, mutations of BAP1 are frequently observed in most metastasizing uveal melanomas." (PMID 35409195, 2022). "Furthermore, BAP-1 carries out a function in the immune regulation; in fact, research has demonstrated the presence of CD3+ and CD8+ infiltrations in cells affected by uveal melanoma with BAP-1 loss, which is usually related to an increased tumor immune evasion." (PMID 36553016, 2022). "However, BAP1-inactivating mutations appear in 40% of uveal melanoma." (PMID 32532044, 2020). "However, it remained unclear whether somatic mutations/deletions of BAP1 have a similarly favorable prognosis in sporadic MM, or if somatic BAP1 alterations are a poor prognostic marker, as is the case for uveal melanoma and clear cell renal cell carcinoma." (PMID 32117751, 2020). "Mutation, genomic deletion of its locus at 3p21 or loss of BAP1 expression has been reported from various tumor types such as non-small cell lung cancer, renal cell carcinoma, gall bladder cancer, mesothelioma and uveal melanoma, and has been linked to poor prognosis in most of them." (PMID 31903168, 2019).